TGFBI (transforming growth factor beta induced)
Diseases named in the same sentence as TGFBI in open-access papers (continued):
Sharing a sentence is not in itself a finding about the gene and the disease.
endometriosis (2 papers, 2021 to 2024). The growth of functional endometrial tissue in anatomic sites outside the uterine body. "This is the first report that has associated TGFBI with endometriosis, and we show the great potential for TGFBI as a diagnostic tool, and even more importantly, as a predictive biomarker for endometriosis." (PMID 34686725, 2021). "All methods converged to TGFBI as the important player from the point of both endometriosis and hypoxia." (PMID 39744178, 2024). "Nonetheless, within this study we showed hypoxia-mediated transcriptome changes characteristic to EuESCs and EcESCs and identified TGFBI as a potential target for further studies addressing therapeutic strategies for endometriosis." (PMID 39744178, 2024). "As the isolated SCs represent a simplified model system, we proceeded to investigate the TGFBI in the context of endometriosis in a physiologically more relevant system represented by the full tissue samples." (PMID 39744178, 2024). "TGFBI mRNA expression in the bulk tissues of EuE from women with endometriosis and controls was higher in the proliferative phase of menstrual cycle compared to the samples from the secretory phase." (PMID 39744178, 2024). "While TGFBI role in endometriosis in the tissues is less clear according to the results from our ex vivo experiments, its roles in fibrosis and angiogenesis cannot be underestimated." (PMID 39744178, 2024). "Having confirmed that TGFBI mRNA levels are dependent on the menstrual cycle phase, we proceeded to the exploration of TGFBI protein expression and localization in tissue samples from women with endometriosis obtained at proliferative or secretory phases." (PMID 39744178, 2024). "Within this study, we showed hypoxia-mediated transcriptome changes characteristic of EuESCs and EcESCs and identified TGFBI as a potential therapeutic target for endometriosis due to its role in fibrosis and angiogenesis." (PMID 39744178, 2024). "Recent studies have demonstrated the increased levels of TGFBI protein in peritoneal fluid and serum of women with endometriosis compared to controls." (PMID 39744178, 2024). "These significantly higher levels of TGFBI in the peritoneal fluid from women with endometriosis in the present study suggest a role for TGFBI in the pathogenesis of endometriosis." (PMID 34686725, 2021). "This study also reports the first time that the proteins COMP, AGT, TGFBI and ANGP4 have been associated with endometriosis." (PMID 34686725, 2021). "Thus, we decided to explore TGFBI expression in a more physiologically relevant system represented by the EuE and/or EcE from women with endometriosis." (PMID 39744178, 2024). "Additionally, we analyzed TGFBI protein signal intensity in 17 EuE from women with endometriosis (6 in proliferative phase and 11 in secretory phase)." (PMID 39744178, 2024). "TGFBI might mediate fibrotic process in endometriosis, therefore targeting TGFBI should be investigated as a potential strategy to reduce fibrosis in endometriosis models." (PMID 39744178, 2024). "For that, we determined TGFBI mRNA level in 45 EuE from women with endometriosis (11 in the proliferative phase and 34 in the secretory phase), and 24 EuE from women without endometriosis (controls, 5 in the proliferative phase and 19 in secretory phase) using qRT-PCR." (PMID 39744178, 2024). "We found TGFBI mRNA expression in EuE from both women with endometriosis and controls to be menstrual cycle phase-dependent, with a higher expression level in the proliferative phase compared to the secretory phase (FC = 4.5, P < 0.0001 and FC = 4.5, P < 0.001, respectively)." (PMID 39744178, 2024). "An investigation of the sample distributions reveals that, in terms of TGFBI values, at the chosen cutoff there is low separation between control and endometriosis samples, meaning a classifier based on TGFBI could potentially be sensitive to slight measurement variations." (PMID 34686725, 2021).
endometriosis (continued). "It is thus extremely important to explore in future studies whether the TGF-β1/TGFBI and TGF-β1/TAGLN signaling axes mediate and consolidate the hypoxia-driven and the inflammation-driven aspects of the endometriosis pathology." (PMID 39744178, 2024). "According to our review of the literature here, COMP, AGT, TGFBI and ANGP4 have not yet been associated with endometriosis, while S100A8, C163A, EGFR and TIMP1 have." (PMID 34686725, 2021). "For three candidate biomarkers, COMP, TGFBI and AGT, with increased levels in the peritoneal fluid no earlier reports in the context of endometriosis were found." (PMID 34686725, 2021).
glaucoma (2 papers, 2008 to 2023). Increased pressure in the eyeball due to obstruction of the outflow of aqueous humor. "Differential expression of motility genes, including capping protein G (CAPG) and transforming growth factor beta-induced (TGFBI), was consistent with the reactive, migratory astrocyte phenotype characteristic of glaucoma, as were ECM remodeling genes, such as GPNMB and TIMP1." (PMID 18822132, 2008).
Hyperglycemia (2 papers, 2012 to 2013). An increased concentration of glucose in the blood. "In contrast, Tgfßi (transforming growth factor beta induced), while responsive to hyperglycemia, responded to diet only in the diabetic condition." (PMID 22701643, 2012).
Insulin resistance (2 papers, 2023 to 2024). Increased resistance towards insulin, that is, diminished effectiveness of insulin in reducing blood glucose levels. "Furthermore, research has confirmed that insufficient sleep can lead to an increase in insulin resistance, and a recent study has shown that TGFBI-deficient mice exhibit resistance to insulin resistance." (PMID 38725646, 2024). "TGFBI KO mice were resistant to adipose tissue hypertrophy, liver steatosis, and insulin resistance." (PMID 36854775, 2023).
liver cancer (2 papers, 2021). An epithelial or non-epithelial malignant neoplasm that arises from the liver. "The expression of 5 TGFβ-responsive genes (IL11, SERPINE1, SMAD7, SNAI1 and TGFBI) was further validated in other liver cancer cell lines." (PMID 34571856, 2021). "However, high TGFBI expression was associated with good DSS, OS, progression-free survival (PFS), and RFS in liver cancer (p < 0.05)." (PMID 34671645, 2021).
metastatic melanoma (2 papers, 2009 to 2021). A melanoma that has spread from its primary site to another anatomic site. "For example, TGFBI upregulation had a detrimental effect on UVM, which was consistent with a previous study showing that human metastatic melanoma express and released a significantly higher amount of TGFBI, rendering TGFBI a potential target for therapeutic interventions." (PMID 34671645, 2021).
metastatic tumor (2 papers, 2008 to 2009). "Only dense methylation of the TGFBI promoter (i.e., 16 methylated CpG sites detected) was found to correlate with metastatic phenotype, with a significantly higher frequency of dense methylation in metastatic tumor samples (6/14, 42.9%) than in primary tumor samples (2/36, 5.6%) (p < 0.05)." (PMID 18834524, 2008).
myopia (2 papers, 2019 to 2023). "With the known prevalence of TGFBI mutations in the Asian population and the high myopia rate, mutation testing is important in this region; subsequently, the five-mutation genetic test was initially introduced in Asian-Pacific populations." (PMID 30760895, 2019).
Nephroblastoma (2 papers, 2023 to 2024). An embryonal neoplasm characterized by the presence of epithelial, mesenchymal, and blastema components. "Lower gene expression levels of lncRNAs H19 and miR-675 (p < 0.05) were observed in nephroblastoma cells, followed by higher gene expression levels of TGFBI than that in normal cells." (PMID 38355574, 2024). "Downregulation of H19 suppresses TGFBI expression by regulating miR-675 levels, thereby promoting apoptosis in nephroblastoma cells." (PMID 38355574, 2024).
ovarian tumors (2 papers, 2012 to 2017). "TGFBI expression was significantly increased in peritoneal tumors compared to primary ovarian tumors." (PMID 28632775, 2017). "This is consistent with other studies demonstrating a down-regulation of βig-H3 in cancer cells and more recent studies demonstrating that the TGFBI gene is frequently hypermethylated in ovarian tumors." (PMID 22949874, 2012).
prostate tumor (2 papers, 2008 to 2018). "In addition, TGFBI promoter hypermethylation was associated with gene silencing in human lung and prostate tumor cell lines." (PMID 18834524, 2008). "Our previous work identified a dense TGFBI methylation pattern in lung tumor cell lines (H522, H810, and H1417) and a metastasized prostate tumor cell line (DU145)." (PMID 18834524, 2008). "In contrast, three lung tumor cell lines (H522, H810, and H1417) and one prostate tumor cell line (DU145) that expressed an undetectable or a much lower level of TGFBI mRNA showed hypermethylation in the TGFBI promoter." (PMID 18834524, 2008). "Direct bisulfite sequencing revealed that the TGFBI gene promoter is hypermethylated in some human lung and prostate tumor cell lines (H522, H810, H1417, DU145), but unmethylated or sparsely methylated in A549, PC3, and BEP2D (papillomavirus-immortalized human bronchial epithelial cells) cell lines." (PMID 18834524, 2008). "Furthermore, promoter hypermethylation correlated with highly reduced expression of the TGFBI gene in human lung and prostate tumor cell lines." (PMID 18834524, 2008). "TGFBI, in contrast, is strongly induced by TGF-β and can promote prostate tumor growth and metastasis." (PMID 29843383, 2018). "Our previous work had defined the methylation status of a total of 49 CpG sites across 0.6 kb of the TGFBI promoter in human tumor cell lines, and we had demonstrated a dense methylation pattern in lung, kidney, and DU145 prostate tumor cell lines." (PMID 18834524, 2008). "TGFBI, as one of the downstream effectors of the TGF-β signaling pathway, has been shown to be expressed ubiquitously in a variety of normal human tissues but is downregulated or inactivated in many human tumor cell lines including lung and prostate tumor cell lines." (PMID 18834524, 2008).
pulmonary fibrosis (2 papers, 2022 to 2023). Chronic progressive interstitial lung disorder characterized by the replacement of the lung tissue by connective tissue, leading to progressive dyspnea, respiratory failure, or right heart failure. "Increased extracellular matrix proteins were previously associated with pulmonary fibrosis, with TGFBI having potential roles in extracellular matrix remodeling, including lung and cardiac fibrosis." (PMID 36348270, 2022).
retinal degeneration (2 papers, 2008 to 2021). Degeneration of the retina. "Our data indicate that transgene expression of TGFBI/BIGH3 induced an age-dependent retinal degeneration, associated with concomitant significantly attenuated cone and rod responses." (PMID 18568131, 2008). "Recently, several studies reported that TGFBI variants and TGFBR1 polymorphisms are related to alleviating cone death in RP, and to retinal degeneration in AMD." (PMID 33946315, 2021).
schizophrenia (2 papers, 2008 to 2024). A major psychotic disorder characterized by abnormalities in the perception or expression of reality. "The function of the protein and its low expression in the brain make TGFBI a less plausible candidate gene for schizophrenia." (PMID 18298822, 2008).
uveal melanoma (2 papers, 2021). A melanoma derived from melanocytes of the uveal tract. "Interestingly, kidney renal clear cell carcinoma (KIRC, n=533) and uveal melanoma (UVM, n=80) concurrently displayed TGFBI and HYAL1 as poor and good biomarkers, respectively." (PMID 34869001, 2021).
adrenocortical carcinoma (1 paper, 2021). "KM analysis showed that high TGFBI expression predicted poor prognosis of CESC, GBM, KIRC, LGG, testicular germ cell tumors (TGCT), and UVM (all p < 0.05) but good prognosis of adrenocortical carcinoma (ACC) and HNSC (all p < 0.05)." (PMID 34671645, 2021).
albinism (1 paper, 2020). A congenital disorder characterized by partial or complete absence of melanin pigment in the eyes, hair, or skin. "The genes identified for MAC were KMT2D, MAB2IL2, ALDH1A3; ASDA were KERA, PAX6, MYOC, TGFBI, and SLC4A11; congenital cataract were CRYBB2, EPHA2, HSF4 and BCOR; infantile nystagmus were CACNA1A and FRMD7; and albinism were OCA2, GPR143, HPS6 and SLC38A8." (PMID 32830442, 2020).
allergic asthma (1 paper, 2015). A asthma with a basis in a pathological type I hypersensitivity reaction. "In our data, TGFBI and FOXN1 do not correlate with each other in normal tissue, while they present negative correlation in Allergic asthma (−0.76); meanwhile, the positive correlation of TGFBI and FZD8 in normal tissue is reversed to be negative in T2D (from 0.63 to −0.86)." (PMID 26450611, 2015).
Atrophy (1 paper, 2022). Any weakening or degeneration, especially through lack of use. "A second category of atrophy inducers consisted of RNAi for the extracellular matrix proteins cg25c and mfas, respectively homologous to collagen COL4A1 and to the collagen-binding protein TGFBI." (PMID 35501350, 2022).
babesiosis (1 paper, 2023). Babesiosis refers to a condition caused by microscopic parasites that infect the red blood cells. "Other identified proteins that differentiated uncomplicated from complicated babesiosis were various complement cascade components (CFI, CFP, C2, SERPING1, C8G), extracellular matrix components (TGFBI), acute phase proteins (ORM1, ITIH2, ITIH4, FGA, TF, RBP4) and lipoproteins (apoE)." (PMID 37353646, 2023).
bone metastasis (1 paper, 2022). Transfer of a neoplasm from its primary site to bones. "In the validation dataset of GSE14020, GJA1, IGFBP6, ITGBL1, SLC44A1, and TGFBI expressions in the bone-metastasis group were different from those in the control group." (PMID 36046013, 2022).
bronchopulmonary dysplasia (1 paper, 2017). Bronchopulmonary dysplasia is a chronic respiratory disease that results from complications related to lung injury during the treatment of infant acute respiratory distress syndrome in low-birth-weight premature infants or from abnormal lung development in older infants. "Indeed, this hypothesis is supported by previous work where periostin and TGFBI are reported to have opposite effects in the lung in mouse models of bronchopulmonary dysplasia." (PMID 28750100, 2017).
Burkitt lymphoma (1 paper, 2022). A rare form of malignant mature B-cell non-Hodgkin lymphoma. "Taken together, these results validate the findings obtained by the methylome array analysis showing specific changes in DNA methylation levels at three CpG sites within the TGFBI gene in endemic Burkitt lymphoma associated with AFB1 exposure." (PMID 35267594, 2022).
calcific aortic valve disease (1 paper, 2025). "Interestingly, human APP and TGFBI are co-expressed in corneal cells and associate together in amyloid-like deposits in calcific aortic valve disease." (PMID 40676215, 2025).
cardiac hypertrophy (1 paper, 2017). "TGFBI over-expression, which was deposited within the ECM, induced a mild degree of concentric cardiac hypertrophy reminiscent of a nearly identical increase of baseline cardiac hypertrophy observed in periostin heart-specific over-expressing mice at 32 weeks of age." (PMID 28750100, 2017).
dilated cardiomyopathy (1 paper, 2024). Cardiomyopathy which is characterized by dilation and contractile dysfunction of the left and right ventricles. "Pseudo bulk RNA-sequencing technologies comparing age-associated cell type-specific gene signature in donor and dilated cardiomyopathy hearts revealed that TGFBI positively correlates with aging in DCM cardiomyocytes, but not in normal donors." (PMID 39041002, 2024).
disc degeneration (1 paper, 2025). "Recent studies have shown that TGFBI may affect the degradation of the extracellular matrix in the intervertebral disc, thereby contributing to the disc degeneration cascade." (PMID 39752341, 2025).
follicular adenomas (1 paper, 2016). "We made the novel observation that TGFβ-induced protein ig-h3 (TGFBI) was found frequently overexpressed in follicular carcinoma compared with follicular adenoma." (PMID 27025787, 2016). "Moreover, we found that minimally invasive FTC tumours have frequent overexpression of TGFBI with respect to follicular adenomas, consistent with the results in a mouse model of FTC." (PMID 27025787, 2016).
Fuchs endothelial corneal dystrophy (1 paper, 2016). Fuchs endothelial corneal dystrophy (FECD) is the most frequent form of posterior corneal dystrophy (see this term) and is characterized by excrescences on a thickened Descemet membrane (corneal guttae), generalized corneal edema, with gradually decreased visual acuity. "Increased levels of TGFBI protein have been identified in corneas of patients with Fuchs’ endothelial corneal dystrophy (FECD)." (PMID 27350955, 2016).
gastrointestinal carcinomas (1 paper, 2015). "In our experiments, we demonstrated that high TGFBI expression is associated with 3 types of gastrointestinal carcinomas in patients and causes tumorigenesis in mice." (PMID 25889002, 2015).
glomerulonephritis (1 paper, 2012). A renal disorder characterized by damage in the glomeruli. "We demonstrated in an anti-glomerular basement membrane model of glomerulonephritis that iNKT cells modulate their pathogenesis through an alternative TGF-β signaling pathway, indicating a renoprotective role for TGF-β-iNKT axis and TGF-β-induced genes (TGFBI/BIGH3)." (PMID 22427838, 2012).
Hyperkeratosis (1 paper, 2021). Hyperkeratosis is a histopathological term defining a thickened stratum corneum and may be present in many different skin conditions, with many possible overlaps. "The overlapping DEGs included genes associated with hyperkeratosis (upregulated LCE3E and TMEM45A), wound healing (upregulated KRT17, IL36G, TNC, and TGFBI), barrier defects (downregulated FRAS1 and BCL11A), and response to infection (upregulated IL36G, ADAP2, DFNA5, RFTN1, LITAF, and TMEM173)." (PMID 34506598, 2021).
Hypocalcemia (1 paper, 2016). An abnormally decreased calcium concentration in the blood. "Moreover, the presence of this TGFBI variant in the father (individual I.4), who was affected with hypocalcemia only, indicates likely nonpenetrance of the mutant allele." (PMID 26818911, 2016).